ST6GAL1 (ST6 beta-galactoside alpha-2,6-sialyltransferase 1)
Diseases named in the same sentence as ST6GAL1 in open-access papers (continued):
Sharing a sentence is not in itself a finding about the gene and the disease.
cancer (continued). "Both genes are commonly amplified in cancer cells due to their shared presence within the 3q26 amplicon, and then the transcribed Sox2 protein binds the ST6GAL1 promoter to further enhance ST6Gal-I expression." (PMID 31610800, 2019). "Having observed coordinate amplification of SOX2 and ST6GAL1 in human tumor tissues, we next examined the copy number status of these genes in the NCI-60 panel of established human cancer cell lines." (PMID 31610800, 2019). "Within the last decade, there has been a renewed interest implicating ST6Gal-1 expression in chemoresistance, TNF and EGF-mediated signal transduction, maintenance of pluripotentency in stem cells, and cancer." (PMID 30778346, 2019). "By the inhibition of crosstalk between ST6Gal1 and PI3K, NDAT enhanced gefitinib-induced antiproliferation in all cancer cell lines that were studied." (PMID 30187356, 2018). "Furthermore, ST6GAL1 activates the epidermal growth factor receptor, supporting KRAS-driven tumorigenesis and cancer cell survival." (PMID 40164585, 2025). "However, aberrant sialylation and elevated ST6GAL1 expression are increasingly recognized as features of CRC and many other cancer types." (PMID 39937175, 2025). "However, ST6GAL1‐low cancer cells showed more significant attraction to CD8+ effector T cells, memory T cells, and M1 macrophages, compared to ST6GAL1‐high cells." (PMID 40847469, 2025). "Our data highlights a previously unappreciated, non-cell-autonomous mechanism linking extracellular ST6GAL1 in cancer pathobiology." (PMID 35676533, 2022). "Strengthened NF-κB signaling by ST6GAL1 in HCC could be supplementary evidence for enhancing progression and chemoresistance in cancer cells." (PMID 34980201, 2022). "Furthermore, ST6GAL1 is released into the extracellular milieu from cancer cells and healthy non-involved sources such as the liver." (PMID 35676533, 2022). "Our findings indicate that cancer cells in the high ST6GAL1 expression group interact with M1 macrophages, Breg, and CD8+ T cells via HEBP1−EGFR, YARS−EGFR, and ICAM1−EGFR, suggesting that CRC patients with high ST6GAL1 expression may benefit from anti‐EGFR therapy." (PMID 40847469, 2025). "Unlike ST6GAL1, there are relatively few studies focusing on the relationship between ST8SIA3 and cancer." (PMID 36611197, 2023).
tumor (95 papers, 2008 to 2026). "Supporting this, GO analysis indicated that ST6GAL1 overexpression in SW48 cells was positively associated with tumor cell wound healing, proliferation, adhesion, and mesenchymal cell differentiation." (PMID 39937175, 2025). "PD-1 pathway blockade partially restores St6gal1-deficient T cells’ ability to control tumor growth." (PMID 41004592, 2025). "Other than this, ST6Gal1 and ST3Gal3 expression has also shown an association with secondary local tumor recurrences in gastric cancer (p = 0.005; p = 0.012)." (PMID 36547200, 2022). "Overall this is fully consistent with the known importance of ST6GAL1-mediated α2,6-sialic acid-linked glycans/glycoproteins in tumor progression and metastasis." (PMID 35676533, 2022). "Increased levels of the glycosyltransferase enzyme ST6GAL1 are often associated with elevated tumour grade and metastasis, and patient prognosis." (PMID 36087249, 2022). "Increased ST6Gal1 expression was reported in pancreatic, prostate, breast, and ovarian cancer, and was implicated as contributing to tumor growth, metastasis, and signal transduction pathways relevant to tumorigenesis." (PMID 35371997, 2022). "Our study characterizes for the first time ST6GAL1 expression loss caused by aberrant ST6GAL1 promoter methylation potentially indicating a tumor suppressive role in bladder carcinogenesis." (PMID 25465919, 2014). "ST6GAL1 loss is caused by aberrant ST6GAL1 promoter methylation potentially indicating a tumor suppressive role in bladder carcinogenesis." (PMID 25465919, 2014). "Since Galectin-1-glycan lattice formation is sensitive to α2,6 sialylation, ST6GAL1 transfer to tumor-associated immune cells may outcompete the PD-1/PDL1 axis to foster immunosuppressive TME." (PMID 40938891, 2025). "Notably, ST6GAL1, which encodes the enzyme that converts nLc4 into α6-sialyl nLc4, was downregulated in tumor tissues, which can further contribute to the accumulation of the nLc4 precursor in BC." (PMID 40706589, 2025). "Together with our in vitro results, we demonstrated that ST6GAL1 upregulation is associated with enhanced malignant characteristics, such as tumor proliferation and migration, indicating that ST6GAL1 may contribute to increased tumor aggressiveness." (PMID 39937175, 2025). "Furthermore, ex vivo micro-CT analysis revealed that overexpression of ST6GAL1 significantly enhanced tumour incidence in long bones and associated bone destruction (left tibias, Chi-square, p = 0.04)." (PMID 38772281, 2024). "While these studies clearly underline the oncogenic potential of ST6GAL1, seemingly contradictory evidence has emerged suggesting it may also have tumor suppressive qualities." (PMID 25465919, 2014). "Indeed, we identified a tumor-specific ST6GAL1 promoter hypermethylation, which appeared to be more frequently associated with poorly differentiated and advanced tumor stages." (PMID 25465919, 2014). "This same region also contains the Sox2 target ST6GAL1, suggesting that coamplification of Sox2 and ST6GAL1 further intensifies ST6GAL1 expression in the tumor." (PMID 40885395, 2025). "To investigate the effect of ST6GAL1 expression on CRC tumor cells, we employed genetic approaches to establish ST6GAL1-overexpressing (ST6GAL1-OE) and ST6GAL1-knockdown (ST6GAL1-KD) tumor cell lines." (PMID 39937175, 2025). "Growth factor-related transcription factors, such as the MYC proto-oncogene—an important regulator of tumor development and progression —were significantly downregulated in ST6GAL1-knockdown Caco2 cells." (PMID 39937175, 2025). "Although expression levels varied across both groups, ST6GAL1 transcription was upregulated in 20 out of 22 tumor samples compared to their adjacent normal counterparts." (PMID 39937175, 2025). "PODXL knockdown reversed the tumor cell aggregation induced by the knockout of β-galactoside α2,6-sialyltransferase 1 (ST6GAL1), which catalyzes the addition of α2,6-sialic acid onto terminal glycans on glycoproteins." (PMID 40843679, 2025).
tumor (continued). "ST6GAL1 is a transmembrane protein but can also be detected extracellularly as soluble form; however, the study of the ability of ST6GAL1 soluble form to mediate intracellular signaling, extracellular signaling, tumor growth or invasion remains incomplete." (PMID 40938891, 2025). "We further validated the expression levels of these genes and found that tumor-promoting genes were upregulated after ST6GAL1 overexpression in SW48 cells but downregulated following ST6GAL1 knockdown in Caco2 cells." (PMID 39937175, 2025). "Altered sialylation, particularly an increase in the overall levels of sialic acid and the upregulation of specific sialyltransferases like ST6GAL1, is also characteristic of cancer and contributes to tumor progression and survival under stress conditions." (PMID 40868286, 2025). "The results showed that ST6GAL1 protein levels were significantly higher in tumor tissues compared to normal tissues (p = 0.007)." (PMID 40847469, 2025). "Prostate cancer provides another compelling example of glycosylation-driven malignancy, with overexpression of ST6GAL1 catalyzing α2,6 sialylation of N-glycans, which promotes tumor growth, invasion, and resistance to apoptosis." (PMID 40868286, 2025). "Both in vitro and in vivo studies have demonstrated that ST6GAL1 promotes tumor growth and invasion." (PMID 40938891, 2025). "Following NA treatment, the ability of ST6GAL1 to promote tumor cell proliferation, migration, and colony formation was significantly inhibited." (PMID 39937175, 2025). "Collectively, these data suggest that ST6GAL1 transcriptionally reprograms tumor cells to enhance proliferation and migration." (PMID 39937175, 2025). "Through transcriptomic and proteomic analyses, we found that four module genes related to tumor progression were upregulated following ST6GAL1 overexpression." (PMID 39937175, 2025). "Anti–PD-1 treatment efficiently suppressed tumor growth in these St6gal1-KO mice during the first week of treatment." (PMID 41004592, 2025). "IHC analysis of subcutaneous tumor sections also confirmed that ST6GAL1 knockdown promotes the infiltration of CD8+ T cells, in line with flow cytometry findings." (PMID 40847469, 2025). "ST6GAL1 expression in tumor tissues showed a positive correlation with a clinical stage based on diagnostic data and with KI-67 expression as determined by IHC analysis." (PMID 39937175, 2025). "Macroscopic images of subcutaneous tumors showed that tumor size and volume were significantly reduced in the ST6GAL1‐KD groups compared to the NC group." (PMID 40847469, 2025). "High ST6GAL1 expression promotes an immune‐activated tumor microenvironment (TME), characterized by increased infiltration of CD8+ T cells and M1 macrophages, thereby improving sensitivity to immunotherapy." (PMID 40847469, 2025). "Our omics results indicated that certain molecules, though not directly sialylated, are affected by ST6GAL1 overexpression, suggesting that sialic acid modification by ST6GAL1 influences tumor cell function." (PMID 39937175, 2025). "Similar results were observed in the immunofluorescence staining outcomes of the subcutaneous tumor tissues from mice, where ST6GAL1 and PD‐L1 exhibited strong colocalization." (PMID 40847469, 2025). "Our single‐cell analysis has elucidated the role of ST6GAL1 in the formation of the CRC TME, highlighting interactions of high ST6GAL1‐expressing tumor cells with B cells, tumor‐associated macrophages, and potential EGFR‐related pathways." (PMID 40847469, 2025). "ST6GAL1, an α-2,6-sialyltransferase, is also overexpressed in several malignancies and contributes to tumor progression." (PMID 40860122, 2025). "It has been reported that specific α2,6-sialylation catalyzed by ST6GAL1 in glycoproteins is closely connected with the chemotaxis of quiescent tumor cells towards metastatic seeding." (PMID 39273449, 2024).
tumor (continued). "Tumor cells often upregulate ST6GAL1, leading to increased α2-6-sialylation of the Fas receptor (FasR) and tumor necrosis factor receptor 1, which suppresses cancer apoptosis and facilitates the formation of secondary tumor sites." (PMID 39349440, 2024). "Next, using an intra-cardiac injection immunocompromised mouse model, we found that upregulation of ST6GAL1 significantly increased the number of metastatic tumours formed by PC3 cells in bone (unpaired t test, p = 0.006)." (PMID 38772281, 2024). "In sum, the present investigation provides a conceptual advance by highlighting a new regulatory mechanism that contributes to the increased expression of ST6GAL1 in tumor cells exposed to an inflammatory milieu." (PMID 39260693, 2024). "Together, these results highlight a novel molecular pathway by which cytokines within the tumor microenvironment stimulate the upregulation of ST6GAL1 in PDAC cells." (PMID 39260693, 2024). "Upregulation of ST6GAL1 impacts oncogenic cell behaviours and can play a key role in tumour growth, survival, metastasis, immune evasion, and resistance to therapy." (PMID 39272811, 2024). "Our in vivo findings demonstrate significantly higher number of osteoclasts in non-tumour bearing tibias in mice that have ST6GAL1 overexpressing tumours in sites beyond bones." (PMID 38772281, 2024). "Our findings show patients with Gleason grade 7–10 prostate cancerhave 2-fold higher ST6GAL1 levels than patients diagnosed with Gleason 6 tumours (unpaired t test, p = 0.0042)." (PMID 38772281, 2024). "Our data shows ST6GAL1 is 1.7-fold higher in prostate-derived tumours growing in bone compared to tumours biopsied at the primary site (unpaired t test, p = 0.0103)." (PMID 38772281, 2024). "The present investigation reinforces prior work by establishing a tumor-promoting function for ST6GAL1 in tumor xenograft and GEM models." (PMID 37643018, 2023). "Regarding the ST6GAL family, ST6GAL1 showed higher expression levels in tumor tissue compared to normal tissue." (PMID 38067186, 2023). "ST6GAL1 is a sialyltransferase whose transformation relates to the growth, invasion, and metastasis of the tumor." (PMID 37374977, 2023). "A tumor-promoting function for ST6GAL1 was elucidated using tumor xenograft experiments with human PDAC cells." (PMID 37643018, 2023). "In CRC, ST6Gal1 expression is higher in tumor compared to normal tissue and interestingly, lower expression is observed in metastatic (stage III and IV) tumors compared to the non-metastatic ones (stage I and II)." (PMID 36106023, 2022). "We were using multiple TNBC and ER+ cell lines to establish that extracellular ST6GAL-1 mediated novel signaling is important for tumor cell survival, proliferation, invasion, and EMT progression." (PMID 35676533, 2022). "First, ST6Gal-1 is found in multiple immune cells so bulk RNA-Seq of tumor tissue will reflect ST6Gal-1 in immune cells as well as the tumor cells making these data more difficult to interpret." (PMID 35041825, 2022). "In the form of a recombinant protein (rST6GAL1) in combination with the exosomes released by tumor cells, these are capable of impacting target tumor cells and compensates for endogenous ST6GAL1 functions." (PMID 35676533, 2022). "Although ST6GAL1 is known to alter the function of a subset of cell surface proteins that have established roles in tumor biology, the molecular mechanisms through which ST6GAL1 mediates protumorigenic effects remain to be fully elucidated." (PMID 36345944, 2022). "Instead, Ingenuity Pathway Analysis of the US7 OE/EV RNA-seq data indicated “increased neoplasia” of the US7 ST6GAL1 OE cells compared to cells with baseline levels of ST6GAL1." (PMID 35371997, 2022). "Synchronously, ST6GAL1 expression in tumor tissues was reduced with the silencing of TINCR (P < 0.05)." (PMID 34980201, 2022). "Generally, there is a correlation between ST6GAL1 mRNA and protein in tumor cells; however, there is an exception." (PMID 35676533, 2022).
tumor (continued). "BACE1, through degradation, can reduce ST6GAL1 enzyme in cancer cells, rendering its inhibitory role in tumour metastasis diminished." (PMID 36087249, 2022). "As hypoxia is a major driver of VEGF mediated angiogenesis, this suggests a potential signaling axis of ST6Gal1/HIF1/VEGF that contributes to tumor growth via angiogenesis." (PMID 36106023, 2022). "Tumor-native ST6GAL1 promotes tumor cell behaviors such as invasion and resistance to cell stress and chemo- and radio-treatments." (PMID 35676533, 2022). "Increasing evidence has shown that ST6GAL1 expression and activity changes are often closely related to tumor proliferation, migration, and invasion." (PMID 33836687, 2021). "The tumor suppressor miR-9 has been shown to inhibit the expression of ST6GAL1, resulting in reduced invasiveness of mouse HCC cells by inhibition of α-2,6-linked sialylation and integrin-β1/FAK signaling pathway." (PMID 33921986, 2021). "It was reported that ST6GAL1 induces the expression of the key tumor-promoting transcription factors Sox9 and Slug." (PMID 33836687, 2021). "Among these sialyltransferases, ST6GAL1 has a crucial role in angiogenesis in cancerous tissues, which protects tumor cells against hypoxia by enhancing HIF-1 signaling." (PMID 32232009, 2020). "One potential reason for this correlative expression is that the SOX2 and ST6GAL1 genes lie within the same amplicon, 3q26, and are coordinately amplified in the vast majority of tumor specimens." (PMID 31610800, 2019). "Studies of HCT116 cells xenografts in the nude mouse model also indicated that NDAT, alone and in combination with gefitinib, reduced PI3K activity, total amount of ST6Gal1 protein, and tumor size compared to single agent gefitinib-treated tumor." (PMID 30187356, 2018). "In a pioneer study on the detection of altered sialylated N-glycan expression in CRC samples, it was demonstrated that the activity of ST6GAL1 is higher in tumor tissues compared to normal counterparts." (PMID 26539643, 2016). "Classification of these samples by tumor subtypes, however showed that ST6GAL1 mRNA expression tends to be downregulated (fold change, FC: 0.36) in muscle-invasive tumors when compared to normal urothelium (NU) (n = 15)." (PMID 25465919, 2014). "For example, recent studies clearly showed that a downregulation of ST6GAL1 activity in colorectal carcinoma cell lines facilitated cell proliferation and tumor growth." (PMID 25465919, 2014). "FGF19, FGF19-reaction (increase), Ang-2-Reaction (decrease), ST6GAL1, Tumor-FGFR4." (PMID 40164125, 2025). "Notably, the ability of ST6GAL1 to promote tumor cell proliferation, migration, and colony formation was significantly impaired following LGALS3BP knockdown in SW48-OE cells." (PMID 39937175, 2025). "As T cell inhibition is particularly relevant to chronic stimulation such as during tumor progression, we tested whether St6gal1-KO T cells were also less efficient in controlling tumor growth in an MC38 tumor engraftment model." (PMID 41004592, 2025). "In our study, we observed a higher IRS of PD‐L1 in ST6GAL1‐positive tumor samples, supporting the notion that ST6GAL1 and PD‐L1 are co‐localized and may interact functionally." (PMID 40847469, 2025). "We found that ST6GAL1 was significantly upregulated in tumor samples than in matched normal samples by analyzing fresh clinical samples from public databases (mean mRNA expression level: tumor vs. normal samples ═ 0.002712:0.000966, P < 0.05, n ═ 22)." (PMID 39937175, 2025). "ST6GAL1 is upregulated in many tumor types, including prostate cancer, where it facilitates bone metastasis, a process that could be counteracted using sialyltransferase inhibitors." (PMID 40885395, 2025). "Similarly, metastatic clones isolated from human tumor cell lines show increased ST6GAL1 expression compared to the parental population, and ST6GAL1 knockdown in the metastatic clones impairs primary tumor growth and metastasis." (PMID 40938891, 2025).